GZMA (granzyme A)
Diseases named in the same sentence as GZMA in open-access papers (continued):
Sharing a sentence is not in itself a finding about the gene and the disease.
tumor (continued). "The immunological findings presented here, including antigen-presentation, antigen-specific immunity and anti-tumor immunity, provide a new mechanism by which GzmA can link innate and adaptive immunity." (PMID 31293597, 2019). "An mRNA-based metric of immune cytolytic activity, defined as average expression of perforin 1 and granzyme A, was devised to quantify anti-tumor immunity." (PMID 30847026, 2019). "Granzyme A (GzmA), together with perforin, are well-known for their cytotoxic activity against tumor or virus-infected cells." (PMID 31293597, 2019). "In conclusion, GzmA is of interest not only because of its newly described adjuvant activity, but also its possible use in tumor therapy." (PMID 31293597, 2019). "Nevertheless, we found that HCC patients with a high potential neoepitope, coupled with a favorable tumor microenvironment, as assessed by high expression of GZMA, low expression of FoxP3 and PDL1, tended to have a prolonged survival." (PMID 31756926, 2019). "Together with the description of perforin and GzmA and GzmB expression in immature DCs, this suggests that GzmB and perforin expression in myeloid cells is not only related to tumor development, but can be considered a general feature of myeloid cells." (PMID 31212684, 2019). "The current study of GzmA will be helpful in laying the groundwork for further basic studies of inflammation or tumor immunity and for establishment of novel vaccine strategies." (PMID 31293597, 2019). "In comparison to placebo, QBKPN administration increased granzyme B (GzmB), granzyme A (GzmA), and perforin (Prf1) expression in the lungs of B16F10 tumor-bearing mice, which were associated with a decrease in tumor burden." (PMID 29399400, 2018). "It represses CTL-mediated tumor cytotoxicity by altering the expression of perforin, granzyme A, granzyme B, Fas ligand (FASL), and IFNγ." (PMID 29486723, 2018). "NKTR-214/RT resulted in increased absolute lymphocyte counts and expression of T cell activation markers (Ki-67, PD-1, granzyme A) in the blood and tumor." (PMID 30400835, 2018). "As expected, the expression of granzyme A was significantly higher in Th1/Tc1Tcc isolated from HM compared to that released from the tumor tissue counterparts." (PMID 29375559, 2017). "TGF-β inhibits T cell-mediated tumor clearance in vivo by specifically inhibiting the expression of five cytolytic gene products, including perforin, granzyme A, granzyme B, Fas ligand, and IFN-γ, in CTLs30." (PMID 28687760, 2017). "The frequencies of tumor-infiltrating IL-10-expressing B cells and the frequencies of granzyme A and perforin-expressing CD4+ T cells were negatively correlated." (PMID 27136203, 2016). "Despite the long-held assumption of gzms as the main agents of cell death induction delivered by perforin, there are relatively few in vivo models where gzmA and B play a decisive role in recovery from pathogen infection or tumour burden." (PMID 21853094, 2011). "At the same time, if the pore-forming pyroptotic function of GSDMB is activated in cancer cells, it may also have anti-tumor effects, which can be triggered in vitro by granzyme A (GZMA) cleavage." (PMID 40452932, 2025). "GZMA was predominantly expressed in T cells, highlighting its role in anti-tumor immune response." (PMID 40104502, 2025). "GZMA+CD8+ T cells promote pyroptosis of tumor cells via GSDMD." (PMID 40924501, 2025). "Similarly, Granzyme A cleaves GSDMB to promote tumour cell death in tumour cells with high expression of GSDMB, which has been shown to be highly expressed in cancer and associated with tumour metastasis." (PMID 38652105, 2024). "Notably, the presence of IFN‐γ in TME can promote the expression of GSDMB in tumour cells and the GZMA‐GSDMB axis efficacy." (PMID 38652105, 2024). "Consistent with our speculation, an increased proportion of CD8+ tumor-infiltrating lymphocytes (TILs), especially granzyme A (GZMA)-positive cells, was detected in MELK knockdown tumors." (PMID 38970074, 2024).
tumor (continued). "Our results indicated that the expression levels of an array of classic and putative tumor suppressor genes, such as P63, Fasl, Gabbr2, and Gzma (granzyme A), were extensively diminished in mouse transplanted tumors following heat-killed P. intermedia treatment." (PMID 38515216, 2024). "Manipulating GZMA activity or its expression levels within the tumor microenvironment could pave the way for innovative cancer therapeutics." (PMID 39228516, 2024). "Lymphocytes might have anti-tumor effects by fostering pyroptosis of GSDMB-positive cells through granzyme A (GZMA)." (PMID 38895114, 2024). "However, Granzyme A and IFNγ were markedly increased, corresponding to the increased tumor infiltration by CTLs and NK cells." (PMID 38612760, 2024). "Granzyme A signaling can act as a pro-inflammatory mediator and induce pro-inflammatory cytokines in several cell types including monocytes, macrophages, endothelial and epithelial cells and fibroblasts, and then affects tumor microenvironments." (PMID 38356716, 2024). "In addition, a low expression of IL12RB1, CD28, CCL3, and GZMA before treatment in the p16- tumour group conferred a higher rate of failure." (PMID 36835246, 2023). "Interestingly, the expression of the toxins granzyme A (GZMA) and Perforin 1 (PRF1), secreted by effector cytotoxic T cells and natural killer (NK) cells, were recently shown to be linked to intra-tumoural immune cytolytic activity." (PMID 38022682, 2023). "Furthermore, we found that the IBI315‐treated group exhibited higher expression of granzyme A in CD8‐positive T lymphocytes infiltrating the PDX‐1 tumor." (PMID 37587833, 2023). "Granzyme A, Granzyme B, perforin, the fas ligand, trail, and IFN were upregulated as a result of these CD8+ effector memory T cells migrating to a distal tumor, which caused cytotoxic effects and inhibited the growth of the distal tumor." (PMID 37507972, 2023). "Moreover, GZMA has been identified as a vital factor in inhibiting tumor growth, promoting apoptosis, and stimulating antigen-specific cytotoxic CD8+ T-lymphocytes." (PMID 37760494, 2023). "However, in untreated cells GZMA expression is higher, probably due to the continuous T cytotoxic response to the tumour cells." (PMID 38022682, 2023). "Based on these observations, we hypothesized that IBI315‐induced pyroptosis in tumor cells may occur through the mediation of granzyme A secretion by cytotoxic lymphocytes, contributing to the cleavage of GSDMB." (PMID 37587833, 2023). "Furthermore, in tumor cells, granzyme A (GZMA) receives IFN-γ released from lymphocytes that cleave GSDMB to produce a similar result to GSDMD-induced pyroptotic cell death, thereby implementing positive feedback regulation to suppress tumors." (PMID 37165005, 2023). "During the remodeling of the immunosuppressive CD8-Tef-APOC2 subpopulation into a tumor-killing CD8-Tef-GZMA subpopulation, the metabolic pattern of exogenous lipid metabolism was gradually replaced by the metabolic patterns of amino acid and endogenous lipid synthesis." (PMID 36497182, 2022). "Similarly, NK cells and CD8+ T cells have been recently shown to trigger tumor clearance via the GSDMB-granzyme A axis, and higher enrichment of NK and CD8+ T cells usually reflects better ICB efficacy." (PMID 35784306, 2022). "Finally, in HCC patients, a low expression of GZMA and F2R in the tumor tissues was correlated with aggressive clinicopathological characteristics and poor prognosis." (PMID 35256589, 2022). "However, the present study revealed that the expressions of GZMA and F2R were positively correlated with PD-1 and PD-L1 and regulated the tumor suppression in PD-1 mAb therapy in both mouse models and HCC patients." (PMID 35256589, 2022). "Santiago’s team showed that GZMA can be involved in tumor development and is a potential prognostic target for various cancers; this may be due to the ability of extracellular GZMA to promote the production of NF-κB-dependent IL6 in macrophages." (PMID 36591509, 2022).
tumor (continued). "Moreover, the low expression of GZMA and F2R was positively correlated with PD-1 and PD-L1, impaired tumor suppression by PD-1 mAb, and also predicted aggressive clinicopathological characteristics and a poor prognosis." (PMID 35256589, 2022). "Importantly, the PAR signal secreted by cytotoxic cells was mainly received by the tumor cells, and the GZMA-F2R contributed to the primary PAR communication signaling pathway network." (PMID 35256589, 2022). "In comparing the occurrence and development of normal tissues and tumor tissues, we found that the expression levels of genes encoding activation and cytotoxic molecules, such as GZMB, GZMH, GZMK, GZMA, and NKG7, increased significantly and had strong correlations with signs of exhaustion." (PMID 35634956, 2022). "In addition, GZMA and F2R were positively correlated with PD-1 and PD-L1 in tumor tissues, while the expressions of F2R and GZMA promoted PD-1 mAb-induced tumor suppression in both mouse model and HCC patients." (PMID 35256589, 2022). "Importantly, the GZMA secreted by cytotoxic cells was demonstrated to interact with the F2R expressed by the tumor cells both in vivo and in vitro." (PMID 35256589, 2022). "Together, these results suggested the failure of GZMA-F2R communication in the tumor tissues." (PMID 35256589, 2022). "Bioinformatic analyses reveal that AGO2 expression is negatively correlated with the mRNA levels of CD3, CD8A, and GZMA in a variety of TCGA human tumor types, indicating AGO2-low tumors have a higher abundance of total and CD8+ T cells and stronger immune cytotoxic activity." (PMID 36323669, 2022). "In our study, GZMA functioned as a tumor suppressor, which was positively correlated with the prognosis of BC, but whether it affected the occurrence and development of BC through cell pyrolysis still needs to be confirmed in vivo and in vitro." (PMID 35464869, 2022). "In addition, Protein vaccination alone led to the increase of CTAL4 antibody titers that correlated with the decrease of tumor burden (SUV ratio), along with increased cd8 and granzyme A (gzma) expression, and decreased PD-L1 expression on tumor cells." (PMID 36341387, 2022). "Together, these results demonstrated that the GZMA-F2R communication-induced tumor suppression might be promoted by the LDPRSFLL motif." (PMID 35256589, 2022). "By facilitating exocytosis of granzyme A, EBAG9 silencing may compensate for a loss in therapeutic index, which may accompany engineering efforts aimed at mitigating on-target/off-tumor effects through reduction of CAR-antigen affinity." (PMID 35821635, 2022). "Incubation of OVCAR3-FSHR target cells plus human PBMCs with D2AP11-TCE led to the significant induction of IFN-γ, soluble Fas (sFas), granzyme A, granzyme B, and perforin compared with empty vector control at 48 hours, and this construct drove robust tumor antigen-specific killing." (PMID 36509287, 2022). "Respectively, they engrafted CT26 cells and B16-F10 cells with recombinant human GSDMB into mice subcutaneously, and found that GZMA/GSDMB pathway-mediated pyroptosis strengthened tumor clearance in the mouse model by enhancing the therapeutic efficacy of antitumor immunity." (PMID 35847844, 2022). "In addition, increased expression of CD8α, CXCL9, CXCL10, Granzyme A (GZMA), Granzyme B (GZMB), and IFN-γ was observed in Six1-deficient tumor tissues." (PMID 34782761, 2021). "Similarly, higher expression of GZMA, STING and fibronectin and lower levels of CD80 were associated with response within tumour compartments." (PMID 35083152, 2021). "Helped CD8+ T cells then upregulate molecules such as granzyme A, granzyme B, perforin, fas ligand, trail, and IFNγ, which play roles in cytotoxic effector function, and may help delay distal tumor growth." (PMID 36405502, 2021).
tumor (continued). "Our tumour compartment specific multivariate signature for response was largely consistent with the DE results, comprising higher levels of fibronectin, GZMA and STING and lower EPCAM and CD80 (AUC = 0.875)." (PMID 35083152, 2021). "Besides the classic GzmB, other inflammatory Gzm, such as GzmA and GzmK, are involved in the anti-tumor activity of immune cells." (PMID 34685542, 2021). "For example, GZMA and AIM2 gene expression in tumor cells was positively associated with increased drug sensitivity to nelarabine, dexamethasone decadron, fluphenazine, arsenic trioxide, procarbazine, olaparib, fludarabine, simvastatin, cyclophosphamide, and asparaginase." (PMID 34721986, 2021). "Finally, comparison of gene expression between early and advanced T cells revealed that the cytolytic molecule GZMA highly expressed in T cells derived from early CRC tumor." (PMID 33463049, 2021). "Similarly, CD8+ T cells and NK cells were recently shown to trigger tumor clearance through the GSDMB-granzyme A axis, and this process is enhanced by IFN-γ." (PMID 32778143, 2020). "The microarray data revealed 728 distinctly regulated genes between two populations and the top highly expressed genes (IL2RB, GZMA, GZMB, EMR4, PRF1, CX3CR1, STAT1, and TLR9) in lung-derived Ly6C+ cells from EMT6 tumor-bearing mice are associated with effector T-cell function." (PMID 30926774, 2019). "However, a higher gene expression of GZMA in the tumor infiltrating lymphocytes correlated with prolonged survival, and a lower expression of FoxP3 or PDL1 further improved the patients’ survival." (PMID 31756926, 2019). "Because regulation of cytolytic CD8+ T cells is crucial in controlling tumor progression and growth particularly through the release of granzymes, we studied the effect of cancer cell line exposed monocytes on granzyme A release in CD8+ T cells." (PMID 29668679, 2018). "However, differential effects were observed in IFNγ, granzyme A and B and Fas ligand expression, crucial effector molecules for tumor immunosurveillance." (PMID 28029653, 2017). "Next, GZMA gene, encoding a secreted granzyme involved in cytotoxic T cell-mediated immune response, is over-expressed in RCC tissues with high contents of natural killer cells and tumor-infiltrating lymphocytes." (PMID 18194544, 2008). "Thus, HOXD10 may be involved in cancer development through the alteration of the tumor microenvironment by granzyme A." (PMID 38356716, 2024). "Transcriptional analysis showed increased expression of cytotoxic genes such as NK markers and Granzyme A in intestinal IEL CD4+ T cells in aged mice, suggesting that intestinal CD4+ T cells in aging individuals may respond to the increased tumor risk by increasing their cytotoxic activity." (PMID 38327516, 2024). "Moreover, GZMA may influence the survival and death of tumor cells within the tumor microenvironment." (PMID 39228516, 2024). "However, TGF-β, produced by tumor cells acts as an immunosuppressive factor that helps cancer cells escape from the immune response by inhibiting the expression of molecules involved in the CTL-mediated tumor cytotoxicity such as perforin, granzyme A, granzyme B, Fas ligand, and IFN-γ." (PMID 37958417, 2023). "CD8+ TMs expressing CCL5 and GZMA, MAIT (mucosal‐associated invariant T) cells expressing TCF7 and PLAC8, and CD4+ TNs (Naïve T cells) expressing CCR7 appeared in paratumour tissues, while CD4+ISG+ T cells expressing ISG15/20 and CD8+ TNs expressing TCF7 only appeared in tumour tissues." (PMID 36855810, 2023). "Furthermore, CD8 + T and NK cells were demonstrated to trigger tumor clearance through the GSDMB-granzyme A axis, which could be enhanced by IFN-γ." (PMID 37635159, 2023). "Granzyme B (GzmB) and Granzyme A (GzmA) are apoptotic proteinase-like serine proteases that can activate caspase-3 and caspase-8 and be transferred to target cells by cytotoxic lymphocytes to trigger cell apoptosis, pyroptosis, and kill virus-infected cells and tumor cells." (PMID 36605130, 2022).
tumor (continued). "Moreover, extracellular cystatin F present in the tumour microenvironment may attenuate granzyme A and B activity and decrease recipient NK cell cytotoxicity." (PMID 33291222, 2020). "Lactic acid repressed the number of CTL that performed lytic granule exocytosis (degranulation) in tumor cell co-culture, and, additionally impaired the quality of the response, as judged by the reduced intensity of degranulation and lower secretion of cytotoxins (perforin, granzyme B, granzyme A)." (PMID 33364193, 2020). "Tumour-specific CD8 T cells subsequently differentiate into effector T-cells, undergo clonal expansion, traffic to the TME, and ultimately kill tumour cells displaying tumour-associated antigen on HLA, via release of cytolytic effector molecules (e.g., granzyme A/B and perforin)." (PMID 29319049, 2018). "In addition, depletion of B7-H4 could help restore CD8+ T anti-tumor immunity by elevating the expression and secretion levels of CD107a, granzyme A, granzyme B, perforin and IFN-γ." (PMID 29113351, 2017). "In line with this possibility, the over-expressed genes in LumA-R2 samples included genes typical of CTLs (and also natural killer (NK) cells), which may lead to anti-tumor cytotoxic activities exerted by the granzyme (GZMA and GZMB) and perforin pathways (PRF1)." (PMID 27386846, 2016). "Murine models of lung AC have demonstrated that Tregs may inhibit CD8+ T cell-mediated anti-tumor immunity, with the depletion of Tregs resulting in tumor cell death and elevated levels of granzyme A, granzyme B, perforin and IFN-γ in infiltrating CD8+ T cells at early stages of tumorigenesis." (PMID 27784305, 2016). "Inducing GSDMB-mediated pyroptosis requires efficient cytosolic delivery of GZMA to cleave GSDMB, a process often thwarted by the membrane repair mechanisms of tumor cells." (PMID 41576171, 2026). "Consistent with our Visium analysis, Xenium gene expression analysis revealed that Tfh-like cells located near tumor regions were enriched for C06b CD103+ Tfh-like signature genes, including CCL5, CCL4, GZMA, HAVCR2, and CSF1." (PMID 41542042, 2026). "The identification of cytolytic enzyme expression levels (perforin, granzyme A, granzyme B, granzyme K, and IFN-γ) provided further insights into the anti-tumor functions of these T cells." (PMID 39979981, 2025). "GZMA-mediated activation of GSDMB induces extensive pyroptosis in target cells, potentially bolstering anti-tumour immunity." (PMID 39901202, 2025). "This study explored the role of perforin-1 (PRF1) and granzymes A, B and K (GZMA, GZMB and GZMK) in cancer biology, focusing on their impact on tumor cell death and immune response modulation." (PMID 40002821, 2025). "Cytotoxic/effector genes (GNLY, GZMA, GZMK, IFNG, NKG7, PRF1) were primarily expressed by T and NK cells, with notable upregulation in stRNA‐seq‐defined invasive front and tumor core regions." (PMID 41057994, 2025). "Among these, GZMK+ CD8+ T cells, GZMB+ CD8+ T cells, and NK cells exhibited high levels of effector cytotoxic genes such as GZMA, GZMB, NKG7, PRF1, and GNLY, contributing significantly to anti-tumor immunity." (PMID 40149859, 2025). "Tumor cells were identified using EPCAM, KRT18, and AFP as markers, while T/NK cells were identified by using the markers CD3D, CD3E, and GZMA." (PMID 40740783, 2025). "After sorting tumour CD8(+)T cells using magnetic bead, perforin, granzyme A, and granzyme B expression were assessed by qRT‐PCR and ELISA." (PMID 39865544, 2025). "For instance, GZMA, TCIM, and OLFML2B were significantly clustered in central (C3) and peripheral (C8) regions of the tumor." (PMID 40104502, 2025). "We found that CXCL16 recruited and activated CD8+ T cells, especially GZMA+CD8+ T cells, a subpopulation of CD8+ T cells that has potent cytotoxicity to tumor cells." (PMID 40924501, 2025). "CYT, an important indicator of the anti‐tumor immune activity of CD8+ cytotoxic T cells, is determined by the expression levels of PRF1 and GZMA." (PMID 41223031, 2025).